IGF1R (insulin like growth factor 1 receptor)
Diseases named in the same sentence as IGF1R in open-access papers (continued):
Sharing a sentence is not in itself a finding about the gene and the disease.
ovarian carcinoma (102 papers, 2010 to 2025). A malignant neoplasm originating from the surface ovarian epithelium. "As a traditional Chinese medicine, ME can prevent ovarian tumors and cause DNA damage to induce ovarian cancer cell apoptosis by inhibiting HSP90AB1/IGF1R." (PMID 37180757, 2023). "In ovarian cancer, strong IGF1R/PCNA colocalization was significantly associated with better disease-specific overall survival (OS) (log rank, p = 0.037)." (PMID 32701997, 2020). "Insulin-Like Growth Factor Receptor 1 (IGF-1R) and Epidermal Growth Factor Receptor 3 (ErbB3) have been implicated as two such drivers of resistance, however their simultaneous role in ovarian cancer chemotherapy resistance remains poorly elucidated." (PMID 31728045, 2019). "IGF1R is a tyrosine kinase receptor already implicated in the control of ovarian cancer cell proliferation." (PMID 28758950, 2017). "A large body of evidence has supported the importance of IGF1R expression in ovarian cancer, and that increased expression of IGF1R is associated with aggressiveness, as well as drug resistance of the disease." (PMID 25874946, 2015). "Initial resistance to cisplatin in ovarian cancer has been associated with increased IGF-1R expression, whereas IGF-1R expression levels decrease in later stages of resistance." (PMID 26191041, 2015). "The present study demonstrated that IGF1R expression is increased in non-BRCA1-mutated ovarian cancer when compared with adjacent normal tissue." (PMID 24765210, 2014). "Higher levels of IGF1 are also found to be associated with increased disease risk, tumour metastasis and poor prognosis in ovarian cancer via the activation of IGF1-R." (PMID 24237932, 2013). "The evidence suggests that IGF-1R both be involved in the mechanisms underlying development of ovarian cancer and confirms the correlation of Lewis(y) and IGF-1R." (PMID 22072919, 2011). "IGF1R has previously been implicated in cisplatin resistance in ovarian cancer." (PMID 29160922, 2018). "Furthermore, IGF1R levels are additionally significantly elevated in BRCA1 inactivation ovarian cancer (BRCA1 mutation or hypermethylated BRCA1 promoter)." (PMID 24765210, 2014). "Notably, the expression levels of IGF1R were markedly increased alongside hypermethylated promoter-mediated BRCA1 deficiency in ovarian cancer." (PMID 24765210, 2014). "In addition, the overexpression of BRCA1 effectively decreased the expression of IGF1R in BRCA1-mutated ovarian cancer cells." (PMID 24765210, 2014). "In addition, BRCA1 knockdown was found to be an effective method of activating IGF1R expression in non-BRCA1-mutated ovarian cancer cells." (PMID 24765210, 2014). "However, BRCA1-mutated ovarian cancer markedly increased the expression of IGF1R compared with the remaining three groups." (PMID 24765210, 2014). "Both IGF-1R and Lewis(y) are associated with the occurrence and development of ovarian cancers." (PMID 22072919, 2011). "For example, in A-673, the combination of Linsitinib, an IGF-1R and insulin receptor inhibitor, with Paclitaxel has shown improved outcomes in refractory ovarian cancer patients." (PMID 41405961, 2025). "IGF, abundantly released in ovulatory follicular fluid, enhances stemness and survival of ovarian cancer cells via activation of the IGF-1R/Akt/mTOR and IGF-1R/Akt/Nanog pathways." (PMID 41373619, 2025). "In our in vitro model using established ovarian cancer cell lines, CAF-C7-derived IGF-I was associated with enhanced IGF1R signaling activity, improved cell survival under anoikis-inducing conditions, and increased migratory behavior." (PMID 41463024, 2025). "To validate the functional impact of IGF1-IGF1R signaling, we performed assays in two ovarian cancer cell lines with relatively high IGF1R expression, including the HGSOC-relevant COV318 and the widely used SKOV3 model." (PMID 41463024, 2025). "High gene and protein expressions of the IGF-1R and IR-A are described in several cancers, including ovarian cancer." (PMID 38396692, 2024).
ovarian carcinoma (continued). "Supportive of this, it has previously been demonstrated that the IGF-1R and IR-A are highly expressed in ovarian cancer cell lines and tissues." (PMID 38396692, 2024). "BRCA1, the well-established susceptibility gene for BCa and ovarian cancer, increases intratumoral IGF-1 protein expression in BRCA mutation carriers suggesting an involvement of the IGF-1/IGF1R axis in BCa pathogenesis." (PMID 36729355, 2023). "The expression and activity of IGF1R are increased in numerous tumor types, including ovarian cancer and rhabdomyosarcoma." (PMID 37180757, 2023). "Together, these results demonstrate that ME treatment repressed the chemoresistance of ovarian cancer cells by attenuating the HSP90AB1/IGF1R signaling pathway and allowing cisplatin to induce DNA damage." (PMID 37180757, 2023). "Sequencing analysis revealed that HSP90AB1 and IGF1R are abnormally upregulated in drug-resistant ovarian cancer cells." (PMID 37180757, 2023). "Activating the ligands of both IGF-1R and ErbB3 promotes ovarian cancer cell proliferation and pro-survival signaling activation, whereas the dual blocking of IGF-1R and ErbB3 enhances the efficacy of relevant chemotherapies." (PMID 36142299, 2022). "For example, a study of ovarian cancer cells has shown that this protein, along with forkhead box O3 (FOXO3a) and hyperactive insulin-like growth factor-1-receptor (IGF1R), plays a very important role in the drug resistance of ovarian cancer cells." (PMID 35715750, 2022). "TMED2 promotes ovarian cancer cell proliferation through activating the IGF2/IGF1R/PI3K/AKT signaling pathway, as described in a previous section." (PMID 35805075, 2022). "It promotes the migration and invasion of ovarian cancer cells by activating the insulin-like growth factor (IGF) 2/IGF receptor (IGF1R)/PI3K/AKT signaling pathway by two molecular mechanisms." (PMID 35805075, 2022). "A recent report showed that higher adhesion to primary lung fibroblasts is associated with escalation of intrinsic and acquired chemoresistance in epithelial ovarian cancer cells, and is largely governed by α6 integrin-IGF-1R dual signaling axes." (PMID 36017326, 2022). "The previous study has shown that miR-217 played an inhibitory role in epithelial ovarian cancer by suppressing IGF1R expression." (PMID 34302635, 2021). "Ex vivo irradiation of ovarian cancer tissue acutely induced IGF1R/PCNA colocalization together with γH2AX-foci formations." (PMID 32701997, 2020). "We further revealed that loss of miR-194-5p expression increases IGF1R and PPFIBP1 expression, leading to increased ovarian cancer cell proliferation, migration and invasion in vitro and tumor growth of ovarian cancer in vivo." (PMID 32284739, 2020). "One study also showed the increased IGF-1R expression in ovarian cancer patients who had been treated with 3–4 cycles of the combination of platinum and paclitaxel regimen." (PMID 32498447, 2020). "In a series of ex vivo irradiated ovarian carcinomas, we found that both low and high dosage of X-ray increased IGF1R/PCNA colocalization together with an increase in γH2AX foci." (PMID 32701997, 2020). "Activating ligands of both IGF-1R and ErbB3 promote ovarian cancer cell proliferation and pro-survival signaling activation, whereas dual blocking of IGF-1R and ErbB3 enhances the efficacy of relevant chemotherapies." (PMID 31728045, 2019). "A survey of ovarian cancer patient samples was performed for IGF-1R, ErbB3, and their respective ligands." (PMID 31728045, 2019). "The sLex-bearing P-selectin ligand is presented on IGF-1R, which is frequently overexpressed in ovarian cancer and other peritoneal metastasis models and confers a poor clinical prognosis." (PMID 31160622, 2019). "Our data indicate a potential benefit of dual IGF-1R/ErbB3 inhibition for ovarian cancer treatment, and highlight the potential impact of istiratumab in combination with standard of care chemotherapy to treat ovarian cancer." (PMID 31728045, 2019).
ovarian carcinoma (continued). "IGF-1R is a robustly expressed RTK in ovarian cancer, and high expression of IGF-1R has been previously shown to correlate with resistance to cisplatin chemotherapy." (PMID 31728045, 2019). "Although we surmise that IGF-1R is functionally relevant for ovarian cancer progression and metastasis, our work suggests that blocking the sLex mediating IGF-1R will be required to provide a promising effect." (PMID 31160622, 2019). "IGF-1R knockdown or signaling inhibition can inhibit ovarian cancer cell proliferation and sensitize cancer cells to platinum-based chemotherapy." (PMID 31728045, 2019). "The complexity of IGF-1R signaling in ovarian cancer requires a deeper understanding and knowledge of the pathway in the disease." (PMID 31728045, 2019). "Here we show that IGF-1R, ErbB3 and their ligands are expressed in a significant proportion of ovarian cancer patient samples." (PMID 31728045, 2019). "Our results suggest a role for IGF-1R and ErbB3 in driving chemotherapy resistance of ovarian cancer." (PMID 31728045, 2019). "Together, these data point to ErbB3 as potentially critical RTK in the treatment of IGF-1R positive tumors, such as ovarian cancer." (PMID 31728045, 2019). "The aim of this work is to determine the effects of dual IGF-1R/ErbB3 inhibition on ovarian cancer cell signaling, growth, and in vivo efficacy." (PMID 31728045, 2019). "IGF-1R can interact with multiple RTKs that are overexpressed in ovarian cancer, such as EGFR, HER2, ErbB3 and c-Met3." (PMID 31728045, 2019). "As a result, strategies to inhibit IGF-1R signaling using blocking antibodies or small molecule signaling inhibitors have been developed and tested in ovarian cancer." (PMID 31728045, 2019). "In A2780 ovarian carcinoma cells, drug resistance to either cisplatin or the combination of cisplatin and Taxol is correlated with the upregulation of IGF-1R expression." (PMID 29867465, 2018). "We have been investigating the effect of IGF1R targeting in endometrial and ovarian cancer for several years." (PMID 29922232, 2018). "Although the involvement of the IGF axis and the IGF1R in ovarian cancer has been widely investigated, the exact function of IGF1R in host immunity and in tumor-infiltrating immune cells is still not clear." (PMID 29922232, 2018). "Next, we examined the expression pattern of other growth factor receptors (c-MET and IGF-1R) and one of the putative ovarian cancer stem cell markers, CD44, in tumour specimens from these patients." (PMID 29731973, 2018). "Our study found that TMED2 regulates epithelial ovarian cancer progression by activating IGF2/IGF1R/PI3K/AKT pathway." (PMID 29212217, 2017). "Over-expression of miR-223 in ovarian cancer cell lines reduces proliferation and colony formation, also by targeting of IGF1R." (PMID 29137392, 2017). "Recent work by our group has demonstrated that TGFβ positively controls ovarian cancer proliferation through the control of insulin like growth factor 1 receptor (IGF1R) expression levels in some orthotopic mouse models (PDX) and ovarian cancer cell lines." (PMID 28758950, 2017). "Herein we for the first time elucidated the role of IGF-1R signaling in enrichment of CSC phenotype during acquirement of chemoresistance in ovarian cancer cells." (PMID 27819360, 2016). "Overexpression of IGF1R is related with poor prognosis in many human cancers besides the renal cancer also in breast and ovarian cancers." (PMID 27405474, 2016). "The IGF-1R pathway was observed to be up-regulated in microarray analysis of Ovarian Cancer tissues while also inversely correlating with survival." (PMID 27472395, 2016). "We have previously developed a computational model of the interactions between IGF1, IGF1R, and IGFBPs in ovarian cancer cells." (PMID 26861122, 2016).
ovarian carcinoma (continued). "Together, our data suggest that IGF-1R-AKT signalling imparts functional heterogeneity in CSCs during acquirement of chemoresistance in ovarian carcinoma." (PMID 27819360, 2016). "It is unclear though, how IGF-1R-AKT signalling shapes CSC functionality especially in ovarian cancer." (PMID 27819360, 2016). "For example, PTP1B, a phosphatase for IGF1R, is expressed at significantly lower levels in ovarian cancer cells compared to normal ovarian surface epithelial cells." (PMID 26861122, 2016). "Our data indicate that over-expressing PRKCZ in certain ovarian cancer cell lines can alter the expression of IGF1R, and the type of expression alteration is cell-line dependent." (PMID 25874946, 2015). "Here, we assessed the correlation between IGF-1R inhibition and HR functionality of breast and ovarian cancers cells, and observed an increased sensitivity of HR deficient cancer cells to IGF-1Rki." (PMID 26510816, 2015). "P-cadherin and p-IGF-1R were significantly co-expressed in peritoneal metastatic lesions compared with paired primary ovarian tumours and, in ovarian cancer cells; GnRH induces the recruitment and formation of an IGF-1R/P-cadherin complex." (PMID 26438065, 2015). "This is consistent with our previous work demonstrating that inhibition of the IGF-1R sensitizes ovarian cancer cells to PARP inhibition." (PMID 26510816, 2015). "Although there is no experimental evidence for the positive association between insulin and ovarian cancer, some studies have shown that the increased serum levels of IGF-1, IGF-1R, and IGFBP-2 were associated positively in patients with ovarian cancer." (PMID 25866823, 2015). "It was also demonstrated that P-cadherin activates migration and invasion of ovarian cancer cells through IGF-1R." (PMID 26438065, 2015). "We thus assessed the expression of downstream proteins of the IGF-1R pathway in the breast and ovarian cancer cells." (PMID 26510816, 2015). "As a result, the present study was undertaken to investigate IGF1R expression from genetic (BRCA1 mutation) and epigenetic (BRCA1 promoter methylation) aspects in ovarian cancer and to provide novel insights into the regulatory mechanism involving IGF1R." (PMID 24765210, 2014). "Recently, IGF1R has drawn considerable interest in the field of epithelial neoplasms, in particular, several types of gynecological malignancies, including ovarian cancer." (PMID 24765210, 2014). "Over expression of IGF-1R in in vivo and in vitro models of testicular and ovarian cancer inhibited Cisplatin-induced apoptosis." (PMID 24885964, 2014). "Breast cancer 1 (BRCA1) and insulin-like growth factor 1 receptor (IGF1R) are critical in ovarian cancer progression." (PMID 24765210, 2014). "A phase I trial of figitumumab, a monoclonal antibody against IGF1R, reported that therapy was well tolerated in combination with chemotherapy, and a complete response was observed in the ovarian cancer patient that was enrolled." (PMID 25115504, 2014). "In a Phase 1 study of AMG-479 (Ganitumab, Amgen, a monoclonal IGF1R antibody) that enrolled 33 epithelial ovarian cancer patients, 3 had an objective response and 5, stable disease (NCT00718523)." (PMID 24904527, 2014). "In conclusion, we achieved satisfactory anti-tumor activity with combination therapy strategy, e.g. trastuzumab plus anti-IGF-1R mAb (LMAb1), in trastuzumab-resistant ovarian cancer model." (PMID 25424625, 2014). "In contrast, IGF-1R staining was significantly increased in epithelial ovarian cancer tissues (n=36)." (PMID 24103397, 2013). "Treatment of primary ovarian cancer cell lines with an IGF-1R AS inhibited growth and proliferation and decreased clonogenicity in soft agar assay." (PMID 24103397, 2013). "Ovarian cancer cells exhibited a distinct band of molecular weight 135,000 representative of the α subunit of the IGF-1R when examined by Western immunoblotting." (PMID 24103397, 2013).
ovarian carcinoma (continued). "In this study, inhibition of IGF-1R expression in primary ovarian cancer cells with an IGF-1R AS induced apoptosis." (PMID 24103397, 2013). "Taken together, these data indicate that the IGF-1/IGF-1R system has a prominent role in the proliferation of human epithelial ovarian cancer cells." (PMID 24103397, 2013). "AS-treated ovarian cancer cells exhibited a corresponding reduction in the amount of detectable phosphorylated IGF-1R." (PMID 24103397, 2013). "The PI3K inhibitor LY294002 efficiently sensitized ovarian cancer cells to cisplatin, similar to IGF-1R AS treatment." (PMID 24103397, 2013). "The present study focuses on the role of IGF-1R in human epithelial ovarian cancer and the antitumor effect of IGF-1R AS." (PMID 24103397, 2013). "Analysis of staining intensity in ovarian cancer tissues indicated that Lewis(y) was linearly correlated with IGF-1R (r = 0.721, P < 0.005)." (PMID 22072919, 2011). "This study aimed to measure and correlate the expression of insulin-like growth factor receptor-1 (IGF-1R) and the Lewis(y) antigen in ovarian cancer cell lines and tissue samples." (PMID 22072919, 2011). "Both IGF-1R and Lewis(y) were highly expressed in ovarian cancer tissues, and their expression levels were positively correlated (P < 0.05)." (PMID 22072919, 2011). "The positivity rates of IGF-1R in ovarian cancer stages III–IV and I–II were 85.71% and 84.62%, respectively, which also was not significant (P > 0.05)." (PMID 22072919, 2011). "The average optical density of IGF-1R in stage III–IV ovarian cancer was 0.444 ± 0.051, which is significantly higher than that in stage I–II (0.413 ± 0.047) (P < 0.05)." (PMID 22072919, 2011). "In order to analyse generalisability of this finding, we correlated IGF-1R mRNA expression with the intrinsic Cisplatin resistance status in a panel of human ovarian cancer cells and found a significant correlation." (PMID 21967738, 2011). "The positivity rate of IGF-1R in ovarian cancer tissues was 93.33%, significantly higher than in borderline tumor (63.33%), benign tumor (53.33%) (P < 0.05), and normal ovarian tissue samples (40%) (P < 0.01)." (PMID 22072919, 2011). "In most cases, the ovarian cancer tissues that highly expressed Lewis(y) antigen concomitantly expressed high levels of IGF-1R; the expression patterns of these were linearly correlated (r = 0.721, P < 0.005)." (PMID 22072919, 2011). "In addition, they show that specific inhibition of IGF1R in DCs decreases ovarian cancer cell migration." (PMID 38420122, 2024). "ME can enhance the sensitivity of ovarian cancer cells to cisplatin toxicity by inhibiting HSP90AB1/IGF1R interactions, and this might represent a novel target for overcoming cisplatin resistance in ovarian cancer chemotherapy." (PMID 37180757, 2023). "Furthermore, miR-1294 was downregulated in ovarian cancer (OC) and clear cell renal cell carcinoma (ccRCC), thereby relaxing its repressive effects on insulin-like growth factor 1 receptor (IGF1R) and homeobox A6 (HOXA6)." (PMID 37303740, 2023). "To investigate whether the HSP90AB1/IGF1R axis is the pathway through which ME ameliorates cisplatin resistance in ovarian cancer cells, we pretreated cells with geldanamycin to inhibit HSP90 ATPase activity prior to treatment with cisplatin and ME." (PMID 37180757, 2023). "Our findings confirmed that HSP90AB1 overexpression could enhance the tolerance of ovarian cancer cells to chemotherapeutic agents by activating drug-resistant proteins IGF1R and MYC, affecting the prognosis of patients." (PMID 36362498, 2022). "Interestingly, P‐cadherin on its own is described to activate invasion and metastasis capacities in ovarian cancer by interacting with IGF‐1R." (PMID 34919784, 2022). "Previously, we discovered FTE could be transformed by follicular fluid (FF) released from ovulation, the most crucial risk factor of ovarian cancer, and IGF axis proteins in FF confers stemness activation and clonal expansion via IGF-1R/AKT pathway." (PMID 33530497, 2021).